RNU6-481P (RNA, U6 small nuclear 481, pseudogene)
Gene: Small nuclear RNA gene on chromosome 1 (161,401,289 to 161,401,395, forward strand). Ensembl gene ENSG00000206921.
Homologues: Orthologues: chimpanzee U6 (98% identical), macaque U6 (93% identical), rat U6 (79% identical), guinea pig U6 (76% identical), mouse Gm56008 (64% identical). Paralogues in human: RNU6-949P (87% identical), RNU6-1024P (86% identical), RNU6-142P (86% identical), RNU6-26P (86% identical), RNU6-338P (86% identical), RNU6-19P (85% identical), RNU6-209P (85% identical), RNU6-31P (85% identical), RNU6-333P (85% identical), RNU6-1011P (84% identical), RNU6-1158P (84% identical), RNU6-12P (84% identical), and 1290 more.